BCL2 (BCL2 apoptosis regulator)
Diseases named in the same sentence as BCL2 in open-access papers (continued):
Sharing a sentence is not in itself a finding about the gene and the disease.
Cerebral ischemia (continued). "Western blot results showed a strong downregulation of Bcl-2 and upregulation of Bax 24 h after cerebral ischemia in the ipsilateral ischemic penumbra area." (PMID 26863436, 2016). "Neuronal death or survival is dependent on the balance between proapoptotic (Bax) and antiapoptotic (Bcl-2) proteins during cerebral ischemia." (PMID 27123035, 2016). "Several studies have shown that Bcl-2 inhibits apoptosis to some extent following cerebral ischemia/reperfusion injury." (PMID 27768719, 2016). "We observed, however, reduced levels of Bcl2 mRNA in infarcted vs. sham tissue, suggesting that the mitochondrial apoptosis pathways were activated by cerebral ischemia." (PMID 26869884, 2016). "We found that either treadmill exercise or MSCs transplantation after cerebral ischemia promoted survivin and bcl-2 expression in the ischemic penumbra at day 14, suggesting that these proteins suppress apoptosis in the ischemic lesion." (PMID 26342636, 2015). "In a study of embryonic stem cell (ESC) transplantation after cerebral ischemia in rats, overexpression of Bcl2 in the ESCs increased survival of the transplanted cells and brought about significant functional recovery in the brain." (PMID 25861413, 2015). "It has been suggested that the over-expression of survivin or bcl-2 protects neurons against cerebral ischemia." (PMID 26342636, 2015). "During cerebral ischemia, ischemic insults result in a reduced Bcl-2 (Bcl-xL)/Bax ratio and shift the balance toward apoptosis by promoting the release of cytochrome c, and Smac/DIABLO from mitochondria." (PMID 26187498, 2015). "The expression of Bax in the hippocampus increased, while the expression of Bcl-2 in the hippocampus decreased following cerebral ischemia." (PMID 25891426, 2015). "TK provides neuroprotection against cerebral ischemia injury by enhancing glial cell survival and migration and inhibiting apoptosis through the suppression of oxidative stress and activation of the Akt-Bcl-2 signaling pathway." (PMID 26451066, 2015). "Neuronal death or survival is determined by the balance between proapoptotic (Bax) and antiapoptotic (Bcl-2 and Bcl-xL) proteins during cerebral ischemia." (PMID 26187498, 2015). "We observed significantly upregulated expression of the antiapoptotic protein Bcl-2 in PACAP38-treated rats 24 hours after cerebral ischemia as compared with that in control rats." (PMID 25523790, 2015). "Histochemical studies showed that GlcNAc-Sal had protective effects against cerebral ischemia-reperfusion insult, then we further examined the possible involvement of Bcl-2, Bax and caspase-3 in GlcNAc-Sal–mediated neuroprotection." (PMID 24991917, 2014). "There is no existing evidence that STAT3 is involved in neuronal apoptosis by the regulation of Bcl-2 and Bax expression following cerebral ischemia." (PMID 25092271, 2014). "Upregulation of Bax and downregulation of Bcl-2 are repeatedly observed in the penumbral area following cerebral ischemia." (PMID 24348730, 2013). "This work represents the first systematic study of the simultaneous changes in bcl-2 gene expression for transient brain ischemia in Wistar rats using real-time PCR technique." (PMID 24250655, 2013). "CREB is known to mediate transcriptional activation of Bcl-2 in many cell types including neurons after cerebral ischemia." (PMID 23251498, 2012). "It is worth of note that CO stimulates the antiapoptotic protein Bcl-2 expression in lung and cerebral ischemia models, and Bcl-2 can translocate into mitochondrial membranes for preventing their permeabilization and cell death." (PMID 22536507, 2012). "The importance of apoptosis in stroke is suggested by the neuroprotection afforded by increased expression of the antiapoptotic Bcl-2 and by the ischemia-induced upregulation of proapoptotic proteins in animal models of cerebral ischemia." (PMID 21673906, 2011).
Cerebral ischemia (continued). "An example is the fact that estrogens upregulate Bcl-2, a protein in itself proven to decrease the damage from cerebral ischemia." (PMID 21673906, 2011). "In the cerebral cortex tissue, we found a significant upregulation of both Bcl-2 and Bax mRNA expression after global cerebral ischemia." (PMID 20158893, 2010). "The regulation of Bcl-2 has widely been considered in the study of the retina as well as in cerebral ischemia." (PMID 19862336, 2009). "Increased Bax and decreased Bcl-2 expressions have been described in several models of cerebral ischemia, and a reduction in antiapoptotic Bcl-xL mRNA following traumatic brain injury has also been reported." (PMID 19862336, 2009). "In our present observations, we found that muscimol could suppress apoptosis in rats of cerebral ischemia by reducing the ratio of Bax/Bcl-2, which was also illustrated in OGD-induced PC12 cells." (PMID 38397792, 2024). "In our study, the results demonstrated that the number of TUNEL-positive cells, Bax, cleaved caspase-3, cleaved caspase-9, PARP, IL-1β, IL-6 and TNF-α protein expression were enhanced after cerebral ischemia‒reperfusion injury, while antiapoptotic Bcl-2 protein expression was decreased." (PMID 37248543, 2023). "In cerebral ischemia, Bcl‐2 was considered as an indicator protein for nerve cell apoptosis." (PMID 36655091, 2023). "However, MTC post-treatment increased the expression of Bcl-2, reduced the expression of Bax and inhibited apoptosis to exert its neuroprotective effect on cerebral ischemia-reperfusion injury." (PMID 35268655, 2022). "Furthermore, ISO was found to suppress the neuron apoptosis in cerebral ischemia/reperfusion injuries in rats, by decreasing the Bax and increasing the Bcl-2." (PMID 35720190, 2022). "Moreover, the Akt/mTOR is a key regulatory pathway of apoptosis, and its activation can upregulate Bcl-2 expression, reduce the ratio of Bcl-2/Bax, and minimize the apoptosis of nerve cells after repeated cerebral ischemia–reperfusion." (PMID 35669881, 2022). "Interestingly, phospho‐CREB is also involved in the upregulation of anti‐apoptotic proteins Bcl2 and Bcl‐xL, which trigger neuronal survival following cerebral ischemia." (PMID 35715988, 2022). "In addition, in rat models of cerebral ischemia, transferring the AM gene to neuron induced anti-apoptotic effects, shown by the overexpression of Bcl-2, p-AKT, and p-GSK-3β." (PMID 34712429, 2021). "Besides, formononetin mediated neuroprotection against cerebral ischemia/reperfusion in rats via downregulation of the Bax/Bcl-2 ratio and upregulation PI3K/Akt signaling pathway." (PMID 33727944, 2021). "Although there was no previous evidence that mentioned the effects of EGCG on Bcl-2 family-related pro-survival pathway in the early aged hypertensive brain, previous studies showed that EGCG enhanced Bcl-2 protein levels in the cerebral ischemia brain and in radiation-induced hippocampal apoptosis." (PMID 34456710, 2021). "In this study, after cerebral ischemia-reperfusion, with the loss of neurological function, the increase of cerebral infarction area and neuronal apoptosis rate, the expression of NR2B and JNK increased, Bax and caspase-3 increased, and Bcl-2 decreased." (PMID 34733340, 2021). "By comparing the effects of moxibustion and Ro25-6981 plus moxibustion on NR2B, JNK, Bax, Bcl-2, and caspase-3 in the cerebral ischemic area, we explored the neuroprotective effect of moxibustion on cerebral ischemia/reperfusion (I/R) injury and its possible mechanism." (PMID 34733340, 2021).
Cerebral ischemia (continued). "Moreover, resveratrol alleviates nerve injury in cerebral ischemia via up-regulation of hippocampal Bcl-2." (PMID 32257906, 2019). "Nesfatin-1 treatment increased Bcl-2 protein level after cerebral ischemia." (PMID 32284834, 2019). "In the present study, however, piracetam markedly inhibited Bax and c-Jun protein expression in hippocampi of rats with cerebral ischemia/reperfusion, and significantly increased Bcl-2, while huperzine A only had a marked effect in terms of decreasing Bax levels." (PMID 26094797, 2015). "In addition, the present study demonstrated that the administration of PQDS increased the level of Bcl-2 expression following cerebral ischemia." (PMID 24348784, 2014). "Bcl-2 provides protection from oxidative stress and cerebral ischemia." (PMID 22348126, 2012). "Previous studies have indicated that IPOC could upregulated Bcl-2 expression, reduced cytochrome c release to the cytosol, and caspase-3 activity thus inhibited apoptosis after cerebral ischemia." (PMID 23029398, 2012). "Additionally, Res significantly increased the expression of the Bcl-2 and decreased the expression of Bax, cleaved caspase-3 and total caspase-3, indicating that it may alleviated cerebral ischemia reperfusion injury by inhibiting neuronal apoptosis." (PMID 41601537, 2026). "In addition, we examined whether retinoic acid inhibits apoptosis and protects brain tissues from cerebral ischemia by controlling the binding of phospho-Bad with 14-3-3 and binding of Bcl-2 and Bcl-xL to Bad or Bax." (PMID 38753710, 2024). "Initiation of the opioid receptor/PI3K/AKT/GSK3β signaling pathway under RIC can also lead to phosphorylation of Bcl-2 and breakdown of the Bcl-2/Beclin-1 complex, which plays an important role in stimulating autophagy and reducing mitochondrial damage in conditioned rats after cerebral ischemia." (PMID 38069355, 2023). "Therefore, it is reasonable to speculate that celastrol may reduce apoptotic neuronal death by inhibiting Bcl-2/Bax dependent caspase-3 activation, thus improve cognitive ability after cerebral ischemia." (PMID 32848589, 2020). "Exercise is reported to exert its therapeutic influence on Alzheimer's disease through the targeting FoxO1(N. Zhao, Xia, & Xu, 2021) and by reducing brain damage by increasing Bcl‐2 and decreasing caspase‐3 and BAX expression in cerebral ischemia." (PMID 36448290, 2023). "For instance, resveratrol has a neuroprotective effect against cerebral ischemia/reperfusion injury by up-regulating the expression of p-JAK2, p-STAT3, p-AKT, p-mTOR, and Bcl2, and down-regulating the expression of cleaved caspase-3 and Bax." (PMID 36940077, 2023). "In addition, urate has been shown to increase the ratio of the mitochondrial anti/pro-apoptotic proteins Bcl-2/Bax in cells expressing mutant superoxide dismutase and decrease levels of the mutagenic deoxynucleotide 8-OHdG in the cortices of rats having undergone focal cerebral ischemia/reperfusion." (PMID 37891890, 2023). "Cerebral ischemia induces a massive release of glutamic acid, which activates the CREB pathway by interacting with NMDA receptors, thus inducing the expression of Bcl-2 and BDNF." (PMID 37242489, 2023). "During cerebral ischemia and reperfusion, ALKBH5 and FTO selectively demethylate Bcl2, preventing degradation of Bcl2 transcripts." (PMID 35706691, 2022). "It has been previously reported that after cerebral ischemia, CREB acts as an important contributor to the survival of neurons by increasing the expression of CRE-mediated genes, including Bdnf and Bcl-2." (PMID 28408940, 2017).
Cerebral ischemia (continued). "Our studies confirmed previous findings that cerebral ischemia reduces the transcript levels of Bcl-2 and showed that upregulation of UCP2 in transgenic mice ameliorated ischemia-induced Bcl2 suppression." (PMID 22348126, 2012). "In a cerebral ischemia model, RES was observed to ameliorate the functional and structural plasticity of synapses in rats with cerebral ischemia, and to upregulate the expression of Bcl‐2 in the hippocampus, thereby counteracting cell apoptosis." (PMID 41019178, 2025). "As expected, we observed a reduction in the apoptotic and necrotic cells, upregulated expression of Bcl‐2, and downregulated expression of cleaved caspase‐3 in the EP+MCAO group compared to the MCAO group, indicating that EP prior to cerebral ischemia exhibited an antiapoptotic effect." (PMID 37143406, 2023). "After 24 or 72 h following global brain ischemia in 15 min, immunoreactivity of both Bcl-2 and Bcl-Xl was noticeable at high levels in CA3 pyramidal neurons and a majority of DG granule cells but not in CA1 pyramidal neurons." (PMID 37452223, 2023). "BAX ablation might be a feasible direction to control cerebral ischemia, which makes MOAP1 critical in cerebral ischemia since it can regulate BAX and BCL2 in neurons." (PMID 35269511, 2022). "Bcl-2 and Bcl-XL overexpression has a significant neuroprotective function in the mature nervous system, in addition, the administration of BCL-XL protein during brain ischemia increased neuronal survival." (PMID 28769794, 2017). "Cytosolic Bcl2 was shown to contribute to MAM formation by localizing to both the ER and the mitochondrial outer membranes and to coordinate ER and mitochondrial Ca2+ homeostasis following cerebral ischemia." (PMID 27777645, 2016). "Pretreatment with PQDS significantly increased the expression of Bcl-2 compared with that in the MCAO group, suggesting that PQDS may mediate the protective effect against cerebral ischemia by inhibiting apoptosis." (PMID 24348784, 2014). "The detailed mechanism of the protective effects of simple O-substituted isoflavones against cerebral ischemia reperfusion might be related to the PI3K/AKT/ERK/mTOR or GSK-3β pathway, eNOS/Keap1/Nrf-2/HO-1 pathway, TLRs/TIRAP/MyD88/NFκ-B pathway, and Bcl-2-regulated anti-apoptotic pathway." (PMID 36142301, 2022). "Due to the similar effects on the protein expression of Bax, c-Jun and Bcl-2 between YXJF and piracetam, it was inferred that the two drugs may share a similar mechanism of action of alleviating memory impairment in rats following cerebral ischemia/reperfusion." (PMID 26094797, 2015). "In addition to PUMA overexpression in CA1 neurons, an earlier study has documented the absence of expression of anti-apoptotic proteins Bcl-2 and Bcl-Xl in CA1 neurons after global brain ischemia." (PMID 37452223, 2023).
Thrombocytopenia (113 papers, 2003 to 2026). A reduction in the number of circulating thrombocytes. "LOXO-338 (Eli Lilly, Indianapolis, IN, USA) is a novel inhibitor of BCL-2, designed to inhibit Bcl-2 over Bcl-xL selectively and to avoid dose-limiting thrombocytopenia associated with Bcl-xL inhibition." (PMID 41303291, 2025). "As anticipated, distinct doses of SIAIS361034 resulted in no appreciable alterations in the number of platelets, whereas the Bcl-2/Bcl-xL dual inhibitor ABT-263 caused severe thrombocytopenia in mice after 8 h of administration." (PMID 36438482, 2022). "We found that ROS scavenger NAC attenuated platelet caspase‐3 activity, decreased the pro‐apoptotic proteins (Bak and Bax) and reversed the loss of anti‐apoptotic proteins (Bcl‐2 and Bcl‐XL), leading to improvement of thrombocytopenia." (PMID 33624364, 2021). "While demonstrating notable efficacy in these studies, in general, systemic BCL-2 inhibition caused lymphopenia, neutropenia, and thrombocytopenia, which required Venetoclax discontinuation in a substantial proportion of patients." (PMID 34063475, 2021). "For example ABT-263 (Navitoclax), an inhibitor of BCL2 has shown clinical efficacy in many haematological cancers, but it causes thrombocytopenia due to interaction with other BCL2 family proteins like BCL-XL and BCL-W24." (PMID 32938954, 2020). "As thrombocytopenia caused by Bcl-XL inhibition limited its clinical use, venetoclax, a selective Bcl-2 inhibitor, was developed." (PMID 32404973, 2020). "Recently, a unique BCL-2–small molecule cocrystal structure was exploited to guide the rational design of venetoclax (ABT-199), a selective BCL-2 inhibitor intended to circumvent thrombocytopenia associated with BCL-XL inhibition." (PMID 28578655, 2017). "Navitoclax (ABT-263), an inhibitor of the pro-survival BCL-2 family proteins BCL-2, BCL-XL and BCL-W, has shown clinical efficacy in certain BCL-2-dependent haematological cancers, but causes dose-limiting thrombocytopaenia." (PMID 25880088, 2015). "Pertinently, GDC-0199, a novel BH3 mimetic developed by Abbott and Genentech that is specific for Bcl-2, and which is now entering clinical trials for lymphoid malignancies, should avoid the dose-limiting thrombocytopenia associated with the navitoclax." (PMID 23171055, 2012). "New‐generation BH3‐mimetics, such as venetoclax (ABT‐199), offer high selectivity for BCL‐2 and substantially reduce the risk of thrombocytopenia compared to earlier multitarget agents like navitoclax, which also inhibits BCL‐XL and destabilizes platelet survival." (PMID 40970582, 2025). "Despite these advances, systemic inhibition of BCL-2 family proteins remains constrained by on-target toxicity, as normal hematopoietic and cardiac cells rely on BCL-xL and BCL-2 for survival, as illustrated by the dose-limiting thrombocytopenia associated with navitoclax." (PMID 41551149, 2025). "The marked increases in patient responses to venetoclax compared to navitoclax across BCL-2-dependent malignancies—for instance, 79% for venetoclax and 35% for navitoclax in CLL—underline that navitoclax, limited by thrombocytopenia, was insufficient to robustly inhibit BCL-2 in patients." (PMID 37685889, 2023). "Although BCL-2 inhibitors represent the first generation of senolytics, their clinical application is limited by their on-target and dose-limiting toxicity associated with hematological issues, such as neutropenia and thrombocytopenia." (PMID 36009552, 2022). "As the first highly selective Bcl-2 inhibitor for clinical use, VEN has an over three orders of magnitude affinity for Bcl-2 than Bcl- XL and Bcl-W, which can greatly improve the problem of dose-dependent thrombocytopenia caused by low selective Bcl-2 inhibitors acting on Bcl- XL." (PMID 36477747, 2022).